CREBBP (CREB binding lysine acetyltransferase )
Description:
Acetylates histones, giving a specific tag for transcriptional activation. Mediates acetylation of histone H3 at 'Lys-18' and 'Lys-27' (H3K18ac and H3K27ac, respectively). Also acetylates non-histone proteins, like DDX21, FBL, IRF2, MAFG, NCOA3, POLR1E/PAF53 and FOXO1. Binds specifically to phosphorylated CREB and enhances its transcriptional activity toward cAMP-responsive genes. Acts as a coactivator of ALX1. Acts as a circadian transcriptional coactivator which enhances the activity of the circadian transcriptional activators: NPAS2-BMAL1 and CLOCK-BMAL1 heterodimers. Acetylates PCNA; acetylation promotes removal of chromatin-bound PCNA and its degradation during nucleotide excision repair (NER). Acetylates POLR1E/PAF53, leading to decreased association of RNA polymerase I with the rDNA promoter region and coding region. Acetylates DDX21, thereby inhibiting DDX21 helicase activity. Acetylates FBL, preventing methylation of 'Gln-105' of histone H2A (H2AQ104me). In addition to protein acetyltransferase, can use different acyl-CoA substrates, such as lactoyl-CoA, and is able to mediate protein lactylation. Catalyzes lactylation of MRE11 in response to DNA damage, thereby promoting DNA double-strand breaks (DSBs) via homologous recombination (HR). Functions as a transcriptional coactivator for SMAD4 in the TGF-beta signaling pathway.
Synonyms: CBP; RTS; KAT3A; MKHK1; RSTS; RSTS1
Tractability: Small molecule: a structure with a bound ligand is known; a high-quality ligand is known; it has a binding pocket of medium quality; it belongs to a druggable protein family. PROTAC: UniProt records ubiquitination sites on it; ubiquitination databases record sites on it; its protein half-life has been measured; a small molecule that binds it is known. Other modalities: a drug acting on it is in phase 2 or 3 trials.
Target class: Epigenetic regulator; Histone acetyltransferase; p300/CBP family; Writer
Chemical probes: A-485 (high quality), CPI-1612 (high quality), CPI-637 (high quality), GNE-049 (high quality), GNE-781 (high quality), I-CBP112 (high quality), ML013, PF-CBP1 (high quality), SGC-CBP30 (high quality)
Gene: Protein-coding gene on chromosome 16 (3,725,054 to 3,880,713, reverse strand). Ensembl gene ENSG00000005339.
Subcellular location: Cytoplasm; Nucleus
Subcellular location (Human Protein Atlas): Nuclear bodies; Nucleoplasm
Pathways (Reactome):
Cellular responses to stimuli: Attenuation phase; Cytoprotection by HMOX1; Heme signaling; NFE2L2 regulates pentose phosphate pathway genes; NFE2L2 regulating ER-stress associated genes; NFE2L2 regulating MDR associated enzymes; NFE2L2 regulating anti-oxidant/detoxification enzymes; NFE2L2 regulating inflammation associated genes; NFE2L2 regulating tumorigenic genes; Nuclear events mediated by NFE2L2; Regulation of NFE2L2 gene expression; Regulation of gene expression by Hypoxia-inducible Factor
Gene expression (Transcription): Activation of the TFAP2 (AP-2) family of transcription factors; FOXO-mediated transcription of cell death genes; MLL4 and MLL3 complexes regulate expression of PPARG target genes in adipogenesis and hepatic steatosis; NPAS4 regulates expression of target genes; Notch-HLH transcription pathway; RUNX1 regulates transcription of genes involved in differentiation of myeloid cells; RUNX3 regulates NOTCH signaling; Regulation of FOXO transcriptional activity by acetylation
Developmental Biology: Activation of anterior HOX genes in hindbrain development during early embryogenesis; Differentiation of naive CD4+ T cells to T helper 2 cells (Th2 cells); Formation of paraxial mesoderm; Regulation of gene expression in late stage (branching morphogenesis) pancreatic bud precursor cells; Transcriptional and post-translational regulation of MITF-M expression and activity; Transcriptional regulation of white adipocyte differentiation; Zygotic genome activation (ZGA)
Circadian clock: BMAL1:CLOCK,NPAS2 activates circadian expression; Expression of BMAL (ARNTL), CLOCK, and NPAS2; Phosphorylated BMAL1:CLOCK (ARNTL:CLOCK) activates expression of core clock genes; Phosphorylation of CLOCK, acetylation of BMAL1 (ARNTL) at target gene promoters; RORA,B,C and NR1D1 (REV-ERBA) regulate gene expression; The CRY:PER:kinase complex represses transactivation by the BMAL:CLOCK (ARNTL:CLOCK) complex
Signal Transduction: Estrogen-dependent gene expression; Formation of the beta-catenin:TCF transactivating complex; NOTCH1 Intracellular Domain Regulates Transcription; NOTCH3 Intracellular Domain Regulates Transcription; NOTCH4 Intracellular Domain Regulates Transcription; Pre-NOTCH Transcription and Translation
and 16 more pathways
Gene Ontology:
Molecular function: acetyltransferase activity; chromatin binding; damaged DNA binding; DNA-binding transcription factor binding; histone acetyltransferase activity; histone H3K18 acetyltransferase activity; histone H3K27 acetyltransferase activity; MRF binding; peptide lactyltransferase (CoA-dependent) activity; protein binding; protein-lysine-acetyltransferase activity; RNA polymerase II-specific DNA-binding transcription factor binding; transcription coactivator activity; transcription coactivator binding; transcription corepressor activity; chromatin DNA binding; tau protein binding; transcription coregulator activity; zinc ion binding
Biological process: cAMP/PKA signal transduction; canonical NF-kappaB signal transduction; cellular response to nutrient levels; negative regulation of transcription by RNA polymerase I; negative regulation of transcription by RNA polymerase II; negative regulation of transcription of nucleolar large rRNA by RNA polymerase I; positive regulation of DNA-templated transcription; positive regulation of double-strand break repair via homologous recombination; positive regulation of protein localization to nucleus; positive regulation of transcription by RNA polymerase II; positive regulation of transforming growth factor beta receptor signaling pathway; regulation of nucleotide-excision repair; embryonic digit morphogenesis; protein-containing complex assembly; regulation of cellular response to heat; regulation of DNA-templated transcription; regulation of smoothened signaling pathway; stimulatory C-type lectin receptor signaling pathway; chromatin remodeling
Cellular component: chromatin; cytoplasm; nuclear body; nucleoplasm; nucleus; cytosol; histone acetyltransferase complex; transcription regulator complex
Genetic constraint (gnomAD): Loss-of-function variants: 17 observed, 253.71 expected, observed/expected ratio (o/e) 0.067, 90% interval 0.045 to 0.1. The synonymous counts are far from expectation, so gnomAD's model fits this gene poorly and the ratio says little. Missense variants: 2,497 observed, 3,241.7 expected, observed/expected ratio (o/e) 0.77, 90% interval 0.74 to 0.8. Synonymous variants: 1,444 observed, 1,250.4 expected, observed/expected ratio (o/e) 1.15, 90% interval 1.11 to 1.21.
Gene-disease validity (ClinGen):
ClinGen rates the evidence that CREBBP causes each of these diseases.
Rubinstein-Taybi syndrome (autosomal dominant): Definitive. A rare malformation syndrome characterized by congenital anomalies (microcephaly, specific facial characteristics, broad thumbs and halluces and postnatal growth retardation), short stature, intellectual disability and behavioral characteristics.
Cancer hallmarks: invasion and metastasis (promotes); escaping programmed cell death (suppresses); proliferative signalling (promotes); genome instability and mutations (suppresses); escaping programmed cell death (promotes)
Homologues: Orthologues: chimpanzee CREBBP (99% identical), macaque CREBBP (99% identical), guinea pig CREBBP (96% identical), mouse Crebbp (96% identical), pig CREBBP (95% identical), rat Crebbp (95% identical), rabbit CREBBP (94% identical), dog CREBBP (91% identical), tropical clawed frog crebbp (77% identical), zebrafish crebbpb (65% identical), zebrafish crebbpa (65% identical), Drosophila melanogaster nej (43% identical), and 5 more. Paralogues in human: EP300 (58% identical).
Diseases named in the same sentence as CREBBP in open-access papers:
CREBBP is named in the same sentence as 269 diseases in open-access papers, as found by Europe PMC text mining. Sharing a sentence is not in itself a finding about the gene and the disease. The quoted sentences say what the papers report.
lymphoma (60 papers, 2014 to 2026). A malignant (clonal) proliferation of B- lymphocytes or T- lymphocytes which involves the lymph nodes, bone marrow and/or extranodal sites. "In lymphomas, inactivating mutations in CREBBP and EP300 facilitate effective immune evasion through impaired neoantigen presentation, including in combination with other chromatin remodeling factors." (PMID 41301688, 2025). "The CREBBP gene is frequently mutated in this type of lymphoma, with changes occurring at the level of the earliest tumor precursor cells." (PMID 40725159, 2025). "Despite selective HDAC3 inhibition showing promise in a subset of lymphomas with CREBBP mutations, wild-type tumors generally exhibit resistance." (PMID 39117798, 2024). "Next to genomic aberrations affecting epigenetic modifiers, such as EZH2, KMT2D, and CREBBP, transcription in is also rewired in GC-derived lymphomas via mutations in the gene encoding the transcription factor MEF2B." (PMID 38124747, 2023). "CREBBP mutations have been identified as an early event in FL evolution that is enriched within lymphoma cell progenitors, which reduces the expression of MHC II on tumor B-cells, thereby promoting immune evasion by reducing antigen presentation." (PMID 36831561, 2023). "The frequency and type of CREBBP/EP300 mutations vary significantly among lymphomas due to different geographic regions or subtypes." (PMID 36831561, 2023). "We applied targeted NGS of 59 lymphoma-related genes and analysed the plasma ctDNA mutation characteristics and found that CREBBP (54%, 15/28) is the most commonly mutated gene in newly diagnosed FL patients." (PMID 37152994, 2023). "We further observed differences in the IC50 values of A-485 in five lymphoma cell lines, indicating a potential correlation between CREBBP/EP300 deficiency and sensitivity to HAT inhibitors." (PMID 33911074, 2021). "HDAC3 inhibition represents a novel mechanism-based immune epigenetic therapy for lymphomas caused by CREBBP mutation." (PMID 34248926, 2021). "Evidence suggests that CREBBP mutations are an early event in lymphoma because mutations in this gene are also found in hematopoietic stem cells." (PMID 34925435, 2021). "EP300 loss‐of‐function also yields a lymphoma tumor suppressor phenotype in mice, and its functions appear to partially overlap with CREBBP in GC B cells." (PMID 30874354, 2019). "In human follicular lymphoma, CREBBP mutations are associated with a significant reduction of MHC class II expression on the lymphoma B-cells." (PMID 31788471, 2019). "We identified novel nonsense and HAT domain mutations in CREBBP, one of which (Y1503H) was previously reported in lymphoma." (PMID 27683039, 2016). "Recent discoveries of the prevalence of inactivating mutations in the acetyltransferase genes EP300 and CREBBP in lymphomas have highlighted the crucial role of epigenetics in the pathobiology of lymphomas, including especially DLBCL." (PMID 25671298, 2015). "Deletions and/or mutations in CREBBP occur in several cancer types including certain leukemia and lymphoma subtypes, adenoid cystic carcinoma, transitional cell carcinoma, small-cell lung cancer, esophageal squamous cell carcinoma and medulloblastoma." (PMID 25423036, 2014). "One of the frequently mutated genes in lymphomas is a transcriptional regulator CREBBP." (PMID 38440231, 2024). "This could explain the low dependence of HBsAg+ FL on CREBBP mutations in that study, as interaction between HBx and CREBBP/p300 might mimic the role of mutant CREBBP during the early stages of lymphoma." (PMID 38482011, 2024). "EP300 and CREBBP are both often mutated in squamous cell carcinoma and lymphomas." (PMID 37705968, 2023). "For example, CREBBP/EP300 gene mutations are frequently detected in diverse lymphomas, such as follicular lymphoma (FL), DLBCL, in situ follicular neoplasia, peripheral T-cell lymphoma (PTCL), angioimmunoblastic T-cell lymphoma (AITL), and plasmablastic lymphoma (PBL)." (PMID 36831561, 2023).
lymphoma (continued). "Furthermore, selective HDAC3 inhibitors restored immune surveillance by reactivating BCL6-repressed INF pathway and antigen presentation genes in lymphoma cells, enabling T-cells to recognize and kill them, especially in the presence of CREBBP mutation." (PMID 35237302, 2022). "Together, we postulate that total loss of CREBBP function may contribute, in part, to the lymphoma genesis." (PMID 33777766, 2021). "The loss of CREBBP promotes the development of HDAC3-dependent lymphoma." (PMID 34211501, 2021). "In developing lymphoma cells, this corruption might reflect pre-GC mutations of CREBBP, while in our screen this oncogenic corruption could be provided by the forced expression of BCL2, BCL6, or MYC." (PMID 31586074, 2019). "Hence, lymphomas with CREBBP mutation become extremely dependent on HDAC3." (PMID 35237302, 2022). "Therefore, EP300 targeted therapy may be another precision approach against CREBBP-mutated GCB-lymphoma." (PMID 35071240, 2021). "The IL4 and BCR-induced mTOR activation was reduced by CREBBP mutants and augmented by mutant STAT6, establishing a link between STAT6 mutations and mTOR regulated pro-growth pathways in lymphoma." (PMID 39910284, 2025). "As for NGS, it would be recommendable to study differential mutational patterns in TCF3 and ID3, which are recurrently mutated in BL, and EZH2, CREBBP, and KMT2D, which are mutated in other lymphomas." (PMID 37672206, 2024). "TET2 and CREBBP mutations are, in the majority of cases, mutually exclusive, so TET2 loss-of-function generates lymphoma cells that show a dependence on HDAC3." (PMID 39518937, 2024). "We suggest low GNAS expression as a potential biomarker that reflects viral mimicry priming for enhanced response to HDAC3 inhibition in the clinical treatment of lymphoma, especially the CREBBP wild-type cases." (PMID 39117798, 2024). "Based on this rationale, HDAC3 loss-of-function or selective HDAC3 inhibition has been recently shown to induce strong anti-lymphoma effects by increasing H3K27ac in CREBBP-mutant lymphoma while those effects are modest in CREBBP wild-type tumors." (PMID 39117798, 2024). "Despite regulating overlapping gene enhancers and pathways, CREBBP and KMT2D mutations recurrently co-occur in germinal center (GC) B cell-derived lymphomas, suggesting potential oncogenic cooperation." (PMID 38570506, 2024). "The consequence of inactivating somatic mutations of CREBBP is promoting the role of HDAC3, which encourages the development of HDAC-3-dependent lymphomas." (PMID 39518937, 2024). "Our findings provide a mechanistic explanation to the frequent coselection of inactivating CREBBP and KMT2D mutations in lymphoma." (PMID 36893259, 2023). "Chromatin writers and erasers are frequently mutated in GC-derived lymphomas, mostly in diffuse large B cell lymphomas (DLBCLs) that show prevalent mutations in major epigenetic modifiers such as EZH2, EP300, CREBBP and KMT2D." (PMID 35580618, 2022). "To conclude, our deep sequencing data revealed recurrent mutations in PCFBCL, such as in TNFRSF14, CREBBP and STAT6, thus classifying this lymphoma subtype as a distinct lymphoma entity within the spectrum of cutaneous lymphomas based on molecular grounds." (PMID 36358692, 2022). "HDAC3 inhibition offers the potential to block the BCL6-HDAC3 complex and restore the key pathways in cell cycle and differentiation inhibited by BCL6 in CREBBP-mutant lymphomas, including Ag presentation as well as BCR, NF-kB, and interferon signaling." (PMID 35071240, 2021).